EGFR (epidermal growth factor receptor)
Diseases named in the same sentence as EGFR in open-access papers (continued):
Sharing a sentence is not in itself a finding about the gene and the disease.
leptomeningeal metastasis (31 papers, 2015 to 2026). Primary or secondary neoplasm in the ARACHNOID or SUBARACHNOID SPACE. "We are currently conducting a prospective, open-label clinical trial titled “Aumolertinib Combined Intrathecal Chemotherapy for Leptomeningeal Metastasis From EGFR-Mutated NSCLC and Prognostic Value of Dynamic Changes in cfDNA Profiles “ (NCT05810350)." (PMID 39949743, 2025). "The benefit of osimertinib treatment was also found to be extended to the subgroup of Chinese EGFR T790M mutation positive NSCLC patients with brain/leptomeningeal metastases reporting a median PFS of 11.0 months (95% CI 9.7–12.4)." (PMID 37316692, 2023). "Up to 40% of NSCLC patients with EGFR mutations treated with EGFR‐TKIs showed disease progression in the central nervous system, such as brain metastases or leptomeningeal metastases." (PMID 37016906, 2023). "Previous studies on the detection of EGFR mutations in cerebrospinal fluid mainly included patients with leptomeningeal metastases." (PMID 33828979, 2021). "enrolled 35 patients with central nervous system metastases, (including 20 brain metastases and 15 leptomeningeal metastases) to investigate EGFR mutational status in cfDNA from paired CSF and plasma samples." (PMID 33828979, 2021). "Another single-arm prospective trial of osimertinib plus bevacizumab in 14 patients with leptomeningeal metastasis (LM) from EGFR mutation showed an LM ORR of 50%, median PFS of 9.3 months, median OS of 12.6 months, and one-year survival rate of 35.7%." (PMID 35046801, 2021). "EGFR mutations were found in the CSF of 9 of 11 (81.8%) patients with leptomeningeal metastases, as compared with three of 10 (30%) patients with brain parenchymal metastases." (PMID 31944608, 2020). "The CSF concentrations of osimertinib were first measured in an NSCLC patient with leptomeningeal metastases and EGFR-TKI resistance." (PMID 36678867, 2023). "Leptomeningeal metastases (LM) is another central nervous system (CNS) disease that occurs in 3–4% of NSCLC patients, and in approximate 9% of those with EGFR mutations." (PMID 36870951, 2023). "Besides, CSF cfDNA could enhance the diagnostic validity for EGFR genotyping of LUAD patients with BM, and reveal frequent occurrence of uncommon EGFR mutations (G719A, L861Q, L703P, and G575R) in patients with leptomeningeal metastasis (LM, 54.5%) than brain parenchymal metastasis (BPM, 10%)." (PMID 34642306, 2021). "The frequency of neurological death due to meningeal carcinomatosis was relatively higher in long-term survival in ALK-positive patients than in EGFR-positive and wild type patients, although the difference was not significant." (PMID 35047245, 2021). "All patients had previously been treated with an EGFR-TKI for a median of 15.0 months (range 6.7 – 20.4 months) prior to the diagnosis of leptomeningeal metastases." (PMID 25784657, 2015). "Herein, we reported an NSCLC patient with leptomeningeal metastasis (LM) who acquired a novel EGFR-SEPT14 fusion during TKI resistance and showed promising responses to certain EGFR TKIs and intrathecal pemetrexed (IP)." (PMID 37554188, 2023). "A total of 10 (47.6%) patients had leptomeningeal metastases (LM), 11 (52.4%) had brain parenchymal metastases (BPM), 5 (23.8%) patients had EGFR mutation‐negative primary tumors at diagnosis, and 13 (61.9%) had positive tumors." (PMID 31944608, 2020).
Stroke (31 papers, 2012 to 2026). Sudden impairment of blood flow to a part of the brain due to occlusion or rupture of an artery to the brain. "EGFR and elevated cystatin C levels are linked to higher stroke risk, while elevated UA levels are associated with both insulin resistance and poor stroke outcomes." (PMID 40667444, 2025). "Cognitive decline in patients with ischaemic stroke has been found to be associated with reduced EGFR expression, which is considered to be an effective indicator of cognitive impairment in stroke patients." (PMID 40137146, 2025). "Those individuals, in whom the mutation accumulates predominantly in EGFr 7–34, have an increased lifetime risk of developing stroke and vascular dementia, albeit with a later onset than in classic CADASIL patients." (PMID 41018180, 2025). "Previous studies have shown that NOTCH3 EGFR 1-6 variants are associated with more severe disease, and our data confirmed this with markedly increased stroke and dementia risk in carriers of EGFR 1-6 variants." (PMID 36300346, 2022). "By comparing CADASIL patients with mutations in EGFr 1–6 and EGFr 7–34, those in the EGFr 1–6 group had a 12-year earlier onset of stroke, lower survival, and higher WMH volume than those in the EGFr 7–34 group." (PMID 32457593, 2020). "NOTCH3 pathogenic variant position is the most important determinant of CADASIL disease severity, with EGFr 7–34 pathogenic variant predisposing to a later onset of stroke and longer survival." (PMID 30032161, 2019). "CADASIL patients with an EGFr 1–6 pathogenic variant have a 12-year earlier onset of stroke than those with an EGFr 7–34 pathogenic variant, lower survival, and higher white matter hyperintensity volumes." (PMID 30032161, 2019). "Regarded as the effectors of mi-RNA, targetgenes such as SP1, AR, and EGFR had the largest number of edges in the network, indicating that they were closely associated with other genes and played significant roles in stroke." (PMID 26830013, 2016). "Specifically, patients with mutations in EGFr 1–6 had an earlier age of stroke onset by 12 years, shorter survival, and increased white matter high-signal volume compared with patients with mutations in EGFr 7–34, which is consistent with a previous study in Japan." (PMID 41018180, 2025). "Based on these models, predictors of an increased risk of shortened stroke-free survival were the number of episodes of mood disturbances, microbleeds and lacunes, while an EGFr mutation location in domains 7 to 34 appeared to delay the occurrence of those events." (PMID 38105268, 2023). "Through network pharmacology and computational simulations, key targets associated with musk volatile compounds and stroke, including SRC, EGFR, ESR1, PTGS2, and DRD2, were identified." (PMID 40137146, 2025). "Yogi and co-workers reported a novel molecular process that, starting from S1P, induced vascular inflammation in stroke-prone SHR rats (SHRSP) through epidermal growth factor receptor (EGFR) and platelet-derived growth factor (PDGFR) transactivation." (PMID 36671552, 2023). "Affected parents of EGFr 1–6 patients also had a significantly earlier onset of stroke than those of EGFr 7–34 patients (median 58 versus 68 years; PLR=0.010) and a lower life expectancy (median 69 years versus 74 years; PLR=0.021)." (PMID 35862191, 2022). "Age at first stroke, survival and white matter hyperintensity volume were compared between 664 CADASIL patients with either a NOTCH3 EGFr 1–6 pathogenic variant or an EGFr 7–34 pathogenic variant." (PMID 30032161, 2019). "In addition, network pharmacological analyses identified 180 potential targets of the major volatile compounds of musk associated with stroke, and five key targets (SRC, EGFR, ESR1, PTGS2, and DRD2)." (PMID 40137146, 2025). "Furthermore, MR blockers were found to diminish the size of cerebral infarcts in stroke-prone hypertensive rats, attributed to the down-regulation of epidermal growth factor receptor mRNA expression." (PMID 37568223, 2023).
Stroke (continued). "Furthermore, EGFR levels are reported to increase in the penumbra surrounding the stroke core in rodents." (PMID 35756121, 2022). "After correction for sex and cardiovascular risk factors, the location of the PV was the highest predictive covariate for age at first stroke, with a hazard ratio (HR) for EGFr 1–6 PV versus EGFr 7–34 PV of 2.63 (95% confidence interval (CI) = 1.61–4.31, P < 0.001, Cox-regression analysis)." (PMID 30032161, 2019). "We could not assess the association of EGFr 10–11 PV with age at first stroke or survival because the number of patients with a PV in the ligand-binding domain in the Dutch CADASIL sample was too low for reliable analysis." (PMID 30032161, 2019). "The results of the correlation analysis showed that 12 variables, including calcium, CPK, monocyte, EGFR, anion gap, glucose, bicarbonate, INR, stroke, AF, smoking, and calcium inhibitor, were significantly correlated with RAR." (PMID 40687564, 2025). "Therefore, SRC, EGFR, ESR1, PTGS2, and DRD2 are closely related to the occurrence and development of stroke, and the volatile compounds of musk may treat nerve damage caused by stroke by binding to these key target proteins." (PMID 40137146, 2025). "The drug design application of the TCM Database@Taiwan has been confirmed by the phosphodiesterase-5 block, epidermal growth factor receptor (EGFR) inhibition, HER 2 receptor inhibition, inflammation inhibition, stroke prevention and against virus." (PMID 24899908, 2014). "There was a statistically significant difference in ALT, anion gap, AST, bicarbonate, calcium, glucose, INR, platelets, total bilirubin WBC, CPK, monocyte, EGFR, RDW, albumin, RAR, sex, calcium inhibitor, race, smoking, stroke, and AF between the survival and death groups (P < 0.05)." (PMID 40687564, 2025). "Interestingly, we have found that, after stroke, aging not only decreases the number of astrocyte-like type B (in both sham and MCAO groups) but also of type-C cells (prominin-1+/EGFR+/nestin−/Mash1+ cells) in the SVZ, in this case, only after injury." (PMID 25958332, 2015). "Five to seven days after the start of the stroke, Tregs infiltrate the brain parenchyma, drive microglial polarization toward the M2 phenotype, and inhibit astrocytic activation by blocking the Amphiregulin (AREG)/Epidermal Growth Factor Receptor (EGFR) pathway." (PMID 38808718, 2024). "NOTCH3 EGFr group is the most important CADASIL disease modifier not only for age at first stroke and WMH volume but also strikingly so for a whole battery of clinically relevant disease measures such as lacune volume and peak width of skeletonized mean diffusivity." (PMID 35862191, 2022). "Though there is a lack of evidence on the correlation between SP1 and EGFR via MAPK cascade in stroke in published literatures, a proper inference could be made in our study." (PMID 26830013, 2016).
urothelial carcinoma (31 papers, 2009 to 2026). A malignant neoplasm derived from the transitional epithelium of the urinary tract (urinary bladder, ureter, urethra, or renal pelvis). "More recently, an analysis of 3753 urothelial carcinoma cases identified one case of an EGFR del19 mutation and three cases of EGFR L858R mutations, all of which affect the tyrosine kinase domain (TKD), with additional cases of exon 20 insertions (27 cases)." (PMID 40364160, 2025). "In this case report, we describe a woman with urothelial carcinoma harboring an EGFR mutation, metastatic to the lung, liver, bone, lymph nodes and brain." (PMID 39057170, 2024). "Whereas EGFR mutations in urothelial carcinomas appear to be rare events, in the TCGA study there was a 9% incidence of EGFR amplification in 131 MIBC samples." (PMID 27438149, 2016). "Inhibition of EGFR function is extremely attractive among the wide array of biological targets implicated in urothelial carcinoma (UC) progression." (PMID 23409107, 2013). "Secondly, the association between EGFR mutation and urothelial carcinoma is also uncommon." (PMID 40364160, 2025). "Moreover, in urothelial carcinoma, whether EGFR mutation should be considered an oncogenic driver as well as the therapeutic management in the case of uncommon EGFR mutation associated with comutations remains also unclear." (PMID 40364160, 2025). "Epidermal Growth Factor Receptor (EGFR) amplifications, which are roughly depicted in 25–50% of urothelial carcinoma, have been correlated with a worse prognosis." (PMID 40364160, 2025). "MUC1-CAR-T cells exhibited selective cytotoxicity against MUC1-positive BC organoids, while combining decitabine with EGFR- or CD44v6-CAR-T cells enhanced cytotoxicity against urothelial carcinoma cell lines." (PMID 41425090, 2025). "Alterations in EGFR family members have also been described in urothelial carcinoma, but there are limited data on the use of EGFR-targeted therapies in this patient population." (PMID 39057170, 2024). "Differences in gene expression and mutational profile were also seen in urothelial carcinoma, which is characterized by overexpression of EGFR and ERBB2 in approximately 70% and 60% of the tumors, respectively, and clinical response to EGFR/ERBB2 inhibitors." (PMID 37414794, 2023). "EGF acts through EGFR to facilitate the development of various types of cancers, including urothelial carcinoma." (PMID 35013128, 2022). "The expression level of EGFR was significant higher in samples with higher stage and grade urothelial carcinoma versus lower stage and grade." (PMID 36581931, 2022). "Here, we report the generation and performance of a NIR-tagged ELP-epidermal growth factor (ELP-EGF) fusion protein to target overexpressed EGFR in urothelial carcinoma (also known as transitional cell carcinoma, TCC)." (PMID 36082359, 2022). "Recently it was shown in urothelial carcinoma cells that SH3BGRL3 can only indirectly interact with EGFR following stimulation of the cells with EGF for 10–30 min and that this interaction occurs through Grb2." (PMID 34380438, 2021). "More recently, anti-EGFR targeted therapies have been evaluated in urothelial carcinomas in a trial demonstrating the benefit of cetuximab combined with paclitaxel as second-line treatment for metastatic bladder cancer." (PMID 33024200, 2020). "Some transcriptional regulators (like forkhead boxA1) and activation of epidermal growth factor receptor (EGFR) pathway also play key roles in squamous differentiation in urothelial carcinoma." (PMID 28789622, 2017). "We analyzed a cohort of 599 cases of urothelial carcinoma for EGFR, ERBB2, and ERBB3 gene expression and genomic alterations." (PMID 28388586, 2017). "A high percentage of EGFR-positive cases (up to 50% of cases) were observed in high-grade urothelial carcinoma." (PMID 25596749, 2015).
urothelial carcinoma (continued). "The epidermal growth factor receptor (EGFR) tyrosine kinase family comprises four members (erbB-1 through erbB-4), with erbB-1 (EGFR) and erbB-2 (Her2/neu) expressed in urothelial carcinoma." (PMID 19918289, 2009). "Furthermore, a novel bispecific ADC targeting both EGFR and HER3, receptors implicated in urothelial carcinoma pathogenesis, has shown promising antitumor activity in a Phase I study across several tumor types, with a good overall response rate." (PMID 41425090, 2025). "We describe here a patient with metastatic urothelial carcinoma with EGFR exon 19 indel which progressed rapidly on standard therapies for urothelial carcinoma but demonstrated prolonged response to osimertinib, which is a third-generation tyrosine kinase inhibitor targeting EGFR." (PMID 39057170, 2024). "The proportion score of EGFR in urothelial carcinoma was high in most of the samples." (PMID 36581931, 2022). "We sought to develop a new intravesical imaging agent that is more specific and sensitive using a polypeptide based NIR (near-infrared) probe designed to detect cells bearing epidermal growth factor receptors (EGFR) that are overexpressed in 80% of urothelial carcinoma (UC) cases." (PMID 36082359, 2022). "EGFR is overexpressed in both human and canine urothelial carcinoma in about 75% of the cases." (PMID 36082359, 2022). "Furthermore, CK14-positive papillary NMIUTUC shared other molecular hallmarks of BASQ-type MIBC: activated p40, c-myc, EGFR, and NF-κB pathways, which mediate growth and squamous differentiation of urothelial carcinoma." (PMID 32391279, 2020). "In essence, urothelial carcinomas could be divided into two distinct categories based on EGFR, ERBB2, and ERBB3 expression and genomic alterations." (PMID 28388586, 2017). "In urothelial carcinoma, the activation of EGFR can upregulate the expression of SOX9 via the ERK signaling pathway, thereby promoting tumor occurrence; the EGFR-ERK-SOX9 signaling cascade mechanism suggests that a similar regulatory pathway may also exist in EGFR-mutated NSCLC." (PMID 41268614, 2026). "Consequently, lessons learned from EGFR targeted treatment in these tumor types may be translated into treatment of Basal/SCC-like urothelial carcinomas." (PMID 28388586, 2017). "In the current study we present our results of the expression of the more commonly used biomarkers VEGF, EGFR and PSMA on LN metastases with urothelial carcinoma." (PMID 36581931, 2022). "Overexpression of EGFR and HER2 is observed in approximately 70% and 60% of canine urothelial carcinoma cases, respectively." (PMID 35027594, 2022). "To clarify the molecular context in which ERBB2 and EGFR gene amplifications and overexpression occur we performed an in-depth study of EGFR, ERBB2, and ERBB3 alterations in relation to existing urothelial carcinoma molecular subtypes." (PMID 28388586, 2017). "Here we investigate EGFR, ERBB2 (HER2), and ERBB3 (HER3) genomic alterations and expression in relation urothelial carcinoma molecular subtypes." (PMID 28388586, 2017). "In analogy with other tumor types, members of the ERBB receptor family have been considered as potential targets also for urothelial carcinomas e.g., ERBB2 (HER2) and EGFR." (PMID 28388586, 2017). "EGFR expression was absent in only 2/17 (12%) primary tumors and in 5/23 (22%) LN metastases with urothelial carcinoma." (PMID 36581931, 2022). "Due to low intensity staining levels in both primary urothelial carcinoma and metastases, EGFR and PSMA are not suitable as target agents for imaging modalities." (PMID 36581931, 2022). "We have previously shown that the antitumor effect of lapatinib in canine urothelial carcinoma cell lines is associated with HER2 expression, but not with EGFR expression." (PMID 35027594, 2022).
urothelial carcinoma (continued). "Urothelial carcinoma cell lines (UCC) and benign uroepithelial HBLAK cells pretreated with the DNMTi decitabine or the HDACi romidepsin were co-incubated with CAR T-cells directed against EGFR or CD44v6, and subsequent cytotoxicity assays were performed." (PMID 34868059, 2021). "Consistent with a role for FEME in EGFR signaling, the stable silencing of Endophilin increases phosphorylation of AKT, GSK3β, SFK and STAT3 after EGF stimulation, mimicking the signaling pattern in urothelial carcinoma." (PMID 32589750, 2020). "We have also determined the dose response of among the urothelial carcinoma cell lines (UM-UC1, UM-UC3, UM-UC5, UM-UC6, UM-UC13, RT4, 253JP, 253J-BV, KU7) to different concentrations of EGFR inhibitor (gefitinib) and PPARγ agonist (DIM-C) after 72 hs of treatment." (PMID 23409107, 2013). "Little evidence is known about VEGF and EGFR as imaging modality targets for urothelial carcinoma." (PMID 36581931, 2022). "EGFR and PSMA do show low staining levels in tumor tissue with urothelial carcinoma and do not seem suitable as target agents." (PMID 36581931, 2022).